KATNAL1 (katanin catalytic subunit A1 like 1)
Description:
Regulates microtubule dynamics in Sertoli cells, a process that is essential for spermiogenesis and male fertility. Severs microtubules in an ATP-dependent manner, promoting rapid reorganization of cellular microtubule arrays (By similarity). Has microtubule-severing activity in vitro.
Synonyms: MGC2599
Tractability: PROTAC: ubiquitination databases record sites on it; its protein half-life has been measured.
Gene: Protein-coding gene on chromosome 13 (30,202,630 to 30,307,551, reverse strand). Ensembl gene ENSG00000102781.
Subcellular location: Cytoplasm, cytoskeleton; Cytoplasm; Cytoplasm, cytoskeleton, spindle pole; Cytoplasm, cytoskeleton, spindle
Subcellular location (Human Protein Atlas): Centrosome; Cytosol; Mitochondria; Mitotic spindle
Gene Ontology:
Molecular function: identical protein binding; microtubule severing ATPase activity; protein binding; ATP hydrolysis activity; ATP binding; microtubule binding
Biological process: microtubule severing; cytoplasmic microtubule organization; spermatogenesis
Cellular component: cytoplasm; cytosol; katanin complex; microtubule; mitotic spindle; spindle; spindle pole; microtubule cytoskeleton; centrosome; cytoskeleton
Genetic constraint (gnomAD): Loss-of-function variants: 28 observed, 43.4 expected, observed/expected ratio (o/e) 0.65, 90% interval 0.48 to 0.88. The upper end of that interval is the gene's LOEUF score, 0.88, which puts it in group 3 of 6, group 1 being the genes least tolerant of losing a copy. Missense variants: 408 observed, 524.69 expected, observed/expected ratio (o/e) 0.78, 90% interval 0.72 to 0.84. Synonymous variants: 176 observed, 167.64 expected, observed/expected ratio (o/e) 1.05, 90% interval 0.93 to 1.19.
Homologues: Orthologues: chimpanzee KATNAL1 (99% identical), macaque KATNAL1 (99% identical), dog KATNAL1 (97% identical), pig KATNAL1 (97% identical), guinea pig KATNAL1 (96% identical), rabbit KATNAL1 (96% identical), rat Katnal1 (95% identical), mouse Katnal1 (94% identical), tropical clawed frog katnal1 (86% identical), zebrafish katnal1 (81% identical), Drosophila melanogaster Kat60 (58% identical), Drosophila melanogaster kat-60L1 (48% identical), and 3 more. Paralogues in human: KATNA1 (68% identical), KATNAL2 (33% identical), FIGNL1 (33% identical), VPS4A (32% identical), SPAST (32% identical), VPS4B (32% identical), FIGN (27% identical), ATAD1 (24% identical), FIGNL2 (23% identical).
Diseases named in the same sentence as KATNAL1 in open-access papers:
KATNAL1 is named in the same sentence as 20 diseases in open-access papers, as found by Europe PMC text mining. Sharing a sentence is not in itself a finding about the gene and the disease. The quoted sentences say what the papers report.
microcephaly (3 papers, 2018 to 2024). A congenital or acquired developmental disorder in which the circumference of the head is smaller than normal for the person's age and sex. "KATNAL1 mutations in humans have been associated with intellectual disability and microcephaly but minimally with ASD (only 1 ASD-related mutation has been reported thus far)." (PMID 38718086, 2024). "Microdeletions on chromosome 13 encompassing several genes, including katanin catalytic subunit A1 like 1 (KATNAL1), were found to result in ID and microcephaly." (PMID 29962938, 2018).
male infertility (2 papers, 2012 to 2023). The inability of the male to effect fertilization of an ovum after a specified period of unprotected intercourse. "Studies in mutant mice indicate that loss-of-function mutations in KATNAL1 disrupt MT function and can cause male infertility by affecting spermatogenesis." (PMID 37895049, 2023). "We therefore deduced that the observed male infertility phenotype in these mice resulted from a single base-pair change encoding a conserved residue of KATNAL1, and that Katnal11H is a recessive loss-of-function allele." (PMID 22654668, 2012). "Subsequent human studies also supported that mutations in the KATNAL1 gene may facilitate male infertility." (PMID 37895049, 2023). "Examination of testicular tissue revealed that KATNAL1 functions to control Sertoli cell microtubule dynamics and retention of sperm during their maturation within the tubules of the testis; absence of KATNAL1 results in premature release of immature sperm and male infertility." (PMID 22654668, 2012).
Azoospermia (1 paper, 2021). Absence of any measurable level of sperm,whereby spermatozoa cannot be observed even after centrifugation of the semen pellet. "The KATNAL1 gene is essential for human spermiogenesis, meiosis, control of Sertoli cell microtubule dynamics, and being affected in cases of azoospermia evidently related to male fertility." (PMID 33800945, 2021).
breast carcinoma (1 paper, 2021). "The excessive microtubule severing driven by KATNAL1-L123V leads to chromosome bridge formation during cell division and the subsequent formation of micronuclei and aneuploidy, which are associated with breast carcinoma pathogenesis." (PMID 34414183, 2021). "The human KATNAL1 mutant L123V identified in breast cancer cells resides in the flexible linker region at the N-terminus of the protein and promotes microtubule-severing activity even in the presence of Tau." (PMID 34414183, 2021).
epilepsy (1 paper, 2020). A brain disorder characterized by episodes of abnormally increased neuronal discharge resulting in transient episodes of sensory or motor neurological dysfunction, or psychic dysfunction. "The epilepsy may be associated with the mutation of KATNAL1 gene or the deletion unmasking a recessive mutation on the other allele, and our findings could provide a phenotypic expansion." (PMID 33023587, 2020).
Infertility (1 paper, 2012). "Utilising random ENU mutagenesis, we have identified a new mouse line displaying male-specific infertility due to a point mutation in the highly conserved ATPase domain of the novel microtubule severing protein KATNAL1." (PMID 22654668, 2012). "Using both classical and molecular genetic analysis we identified Katnal1 as the gene responsible for the infertility phenotype." (PMID 22654668, 2012).
retinoblastoma (1 paper, 2022). A malignant tumor that originates in the nuclear layer of the retina. "TSTD1, CDKN2C, NUCB2, and KATNAL1 showed the most significant MYCNARB1PRO-specific downregulated expression pattern among the hypermethylated genes in this retinoblastoma subtype." (PMID 36245757, 2022).
schizophrenia (1 paper, 2018). A major psychotic disorder characterized by abnormalities in the perception or expression of reality. "Thus the range of phenotypes associated with defects in the function of Katnal1 strongly suggests that the gene should be considered in the pathology of disorders such as ID and schizophrenia." (PMID 28373692, 2018).
Sepsis (1 paper, 2022). Sepsis is defined as life-threatening organ dysfunction caused by a dysregulated host response to infection. "This study indicated that circ-Katnal1 was a promising therapeutic biomarker for sepsis-induced liver injury." (PMID 35979014, 2022). "Taken together, circ-Katnal1 enhanced inflammatory pyroptosis in sepsis-induced liver injury through the miR-31-5p/GSDMD axis." (PMID 35979014, 2022). "In summary, downregulating circ-Katnal1 attenuated proinflammatory cytokine production and inflammatory pyroptosis during CLP-induced sepsis via upregulating miR-31-5p and downregulating GSDMD." (PMID 35979014, 2022).
neurodevelopmental disorder (2 papers, 2018). A behavioral and cognitive disorder with onset during the developmental period that involves impaired or aberrant development of intellectual, motor, or social functions. "Nevertheless, it is evident that KATNAL1 plays an important role during several neuronal processes, and that perturbations of KATNAL1 function can lead to various defects which may eventually contribute to neurodevelopmental disorders." (PMID 29962938, 2018).
KATNAL1 also shares sentences with these, for which no sentence is quoted: Intellectual disability (2 papers); sterility (2); Anxiety (1); ciliopathies (1); cognitive deficits (1); genetic disorder (1); infection (1); Lissencephaly (1); Oral squamous cell carcinoma (1); Rett syndrome (1).